EGFR (epidermal growth factor receptor)
Diseases named in the same sentence as EGFR in open-access papers (continued):
Sharing a sentence is not in itself a finding about the gene and the disease.
cancer (continued). "These compounds were designed to have the essential pharmacophoric features of EGFR Inhibitors, they have shown anticancer activities against HCT116, MCF-7 and Hep3B cancer cells with IC50 values ranging from 0.009 to 2.195 μM." (PMID 35801486, 2022). "The gene ontology (GO) analysis of differentially expressed miRNA (DEM) target genes identified the predominant involvement of epidermal growth factor receptor (EGFR), tyrosine kinase inhibitor resistance, and pathways in cancer in PTC." (PMID 35681658, 2022). "Preclinical studies have shown that gefitinib increased the response to carboplatin and docetaxel; doxazosin reduced EGFR expression; epertinib inhibited EGFR and HER2; almonertinib inhibited the multi-resistance of cancer cells." (PMID 36158981, 2022). "We observed that the expression of 26 cancer driver genes is downregulated by fb-PMT, representative examples of which include EGFR, NOTCH1/2, MAPK1, CCND1, and BRAF." (PMID 36879662, 2022). "Epidermal growth factor receptor (EGFR), a receptor tyrosine kinase (RTK), is a well-known oncogenic driver and a therapeutic target in several types of human cancer." (PMID 35650607, 2022). "Overexpression of miR-302a can block CD44-mediated EGFR/RAS/RAF/MAPK and EGFR/PI3K/AKT signaling pathways and the cancer stem cells (CSC)-like properties in a dose-dependent manner, thereby restoring CRC sensitivity to Cetuximab." (PMID 36131281, 2022). "Inhibition of EGFR also led to downregulation of PI3K, AKT, ERK and interestingly ABCG2, antiporter reported to facilitate development of cancer drug resistance." (PMID 35813479, 2022). "DAG, which is generated by PLCγ docked in EGFR, induces survival signaling in TKI-resistant cancer cells by activating PKCδ." (PMID 35565351, 2022). "The function of CALM1 depends on the synergy of ERGF, and similar to anti-EGFR antibodies, CALM1 inhibitors play an essential role in cancer chemotherapy." (PMID 35433683, 2022). "Ligand activation of EPHA2 or EPHA2 knockdown by small interfering RNA inhibited EGF-induced cell motility of EGFR-overexpressing human cancer cells, indicating a functional role of EPHA2 in EGFR-expressing cancer cells." (PMID 36297233, 2022). "Tyrosine kinase inhibitors (TKI), molecular-targeted drugs, inhibit specific oncogenic drivers, such as the epidermal growth factor receptor (EGFR) and anaplastic lymphoma kinase (ALK), which trigger cancer evolution." (PMID 36434641, 2022). "After that, we compared the expression of cancer biomarkers ATM, BRCA1, PDCD1, and EGFR gene in the two groups." (PMID 36226174, 2022). "Among antibodies, two clinically approved monoclonal antibodies, cetuximab (anti-EGFR) and trastuzumab (anti-HER-2) were used to functionalize AuNPs for enhanced cancer radiotherapy or to depict and quantify high and low tumoral surface marker expression." (PMID 35887030, 2022). "Much effort has been devoted over the past decade in extensively highlighting the tumorigenic properties of AnxA6 in several cancer types, as well as in the resistance of TNBC to EGFR-TKIs." (PMID 35267416, 2022). "Several TKIs or anti-cancer drugs, including cabozantinib and gefitinib, can inhibit HGF/c-MET-, ANG-2/Tie-2-, and/or EGF/EGFR-mediated signaling." (PMID 35008398, 2022). "The expression of components of several cancer-related signaling pathways, such as Mammalian Target of Rapamycin (MTOR), PI3K/AKT, Insulin-like Growth Factor-1 (IGF-1) and Epidermal Growth Factor Receptor (EGFR) pathways are frequently disturbed in LUAD." (PMID 36446361, 2022). "Targeting AXL overcomes acquired resistance to osimertinib and other EGFR-TKIs38,39, and multiple AXL inhibitors have been developed and advanced to clinical trials involving cancer therapy to overcome drug resistance." (PMID 35643725, 2022). "Because single amplification of MET rarely contributes significantly to cancer development, co-mutant of MET and other cancer drivers, such as EGFR, appear more commonly." (PMID 36619616, 2022).
cancer (continued). "AMPK regulates oncogenic signaling downstream of EGFR overexpression and EGF stimulation in other cancer contexts, suggesting AMPK as a potential link between EGFR and GABP regulation." (PMID 36130485, 2022). "Toxic ·OH and low-dose doxycycline (DOX) are effective in synergistically inducing apoptosis of cancer cells and inhibiting EGFR and its downstream AKT/NF-κB/IκB signaling pathway, enhancing the effect of cancer treatment." (PMID 35571530, 2022). "Univariate analysis revealed that there was a significant correlation between the incidences of irAEs and EGFR-TKI therapy history (p = 0.025), ICI cycles (p = 0.009), cancer types (p = 0.009) and Eos (p < 0.037)." (PMID 36438818, 2022). "For the other treatment targets, although some of them were previously identified in other cancers, the large majority are described here for the first time in PitNETs, such as EMT, EGFR T693 phosphorylation, CDK6 and PDL1." (PMID 36307579, 2022). "In this study, we assessed the involvement of EGFR and HER2 in the anti-cancer actions of afatinib in UM cells." (PMID 35781872, 2022). "Targeting both EGFR and SOCE simultaneously will provide synergetic anticancer effects to kill the cancer cells and effectively avoid their adaptive responses." (PMID 35163685, 2022). "Recent studies have argued for an antagonistic cross-talk between the EGF signal transduction pathway and type I interferon response in cancer cells emerging through the activity of HER2, a co-receptor of EGFR and an important drug target." (PMID 35563635, 2022). "In this work the proof of concept was performed by using siRNA directed against epidermal growth factor receptor (EGFR), a molecular target of several cancers, complexed with lipofectamineTM." (PMID 35892854, 2022). "We found STYK1 as a potential target for a combination therapy with EGFR inhibition in NSCLC and demonstrate that STYK1 downregulation improves the anti-cancer effects of EGFR TKI in vitro." (PMID 35840561, 2022). "Seven anti-HCC core targets (CASP3, EGFR, ERBB2, mTOR, MMP9, HIF1A, and PPARG) followed the pathways in cancer." (PMID 35959427, 2022). "Of these DEGs, 6 (EGFR, GATA3, DIABLO, CFLAR, RIPK3, and MAPK8) were repressed, while (ZBP1, PLK1, SPATA2, BCL2, ALK, FASLG, TNFRSF21, and LEF1) were upregulated in cancer cases." (PMID 35610275, 2022). "The expression levels of EGFR, HSP90AA1, and SRC at the transcriptional level of RC were significantly different between normal and cancer tissues (all p < 0.05)." (PMID 36569844, 2022). "It is well acknowledged that EMT is a key driver of cancer metastasis, but EMT also can override the cytostatic effects of anti-EGFR therapy by increasing Snail and AXL expression." (PMID 35279145, 2022). "N-terminally located EGF repeats present in LAMC2 are cleaved by MMP-2 or MT1-MMP and activate EGFR and the MAPK pathway to foster migration and survival of cancer cells." (PMID 36076232, 2022). "Some targets, including EGFR, PDGFR, FAK, CXCR4, and MMP9, have corresponding inhibitors that have been approved or are under active clinical trials for cancer treatment." (PMID 35919862, 2022). "Consistent with this, we found that EGFR-mut cancers conserved more homeobox genes and genes related to RNA Polymerase II compared to KRAS-mut and NEK cancers." (PMID 36612014, 2022). "In cancer clinics, upregulated EREG expression predicts a poor prognosis, but potentially benefits from therapies involving anti-EGFR agents such as panitumumab." (PMID 36202915, 2022). "On the other hand, SRC, CASP3, EGFR, ERBB2, mTOR, MMP9, and HIF1A followed the proteoglycans in cancer." (PMID 35959427, 2022).
cancer (continued). "Then, we validated them by molecular docking analysis with some cancer-related PTM-sites (phosphorylation, succinylation, and ubiquitination) of the four top-ranked key proteins EGFR, AURKB, BIRC5, and TOP2A." (PMID 36567949, 2022). "We have given special attention to betulinic acid mediated regulation of JAK/STAT, VEGF, EGF/EGFR, TRAIL/TRAIL-R, AKT/mTOR and ubiquitination pathways in the inhibition of cancer." (PMID 36615262, 2022). "The network results demonstrated that seven anti-HCC core targets (CASP3, EGFR, ERBB2, mTOR, MMP9, HIF1A, and PPARG) followed the pathways in cancer (degree 7)." (PMID 35959427, 2022). "Analyses of gene dependencies found GAB1 and EGFR were most closely related, highlighting the importance of GAB1 for EGFR-driven cancers, like HNSCC." (PMID 36506869, 2022). "The elevated EGFR, PI3K/Akt, and NF-kB activation was also previously reported to develop chemoresistance/drug resistance in numerous cancers, whereas EGFR, PI3K/Akt, and NF-kB were previously reported to be regulated by ubiquitination and deubiquitination." (PMID 36338727, 2022). "For example, curcumin has been shown to increase cell cycle arrest and disrupt vascular endothelial growth factor (VEGF), epidermal growth factor receptor (EGFR), and cyclooxygenase-2 (COX-2) pathways in numerous cancer cell lines." (PMID 36296810, 2022). "Several parameters were tested, including cellular proliferation, cell cycle regulation, apoptosis, relative expression of VEGFR2, EGFR, MMP-9 and CASPASE3 and the protein levels of pVEGFR2 and pSTAT3 in HepG2 cancer treated cells." (PMID 36284117, 2022). "Not only have EGFR-mutant tumors demonstrated increased VEGF dependence compared to EGFR-wildtype tumors, but VEGF inhibitors have also demonstrated the ability to enhance antitumor activity in EGFR T790M positive cancer cells." (PMID 35841410, 2022). "Here, we used affibody molecules targeting two cancer biomarkers, the receptors HER2 and EGFR, along with the KDEL signal peptide to construct two cancer-specific ricin-based RITs, HER2Afb-RTA-KDEL and EGFRAfb-RTA-KDEL." (PMID 35999603, 2022). "EGFR and HER2 have emergedas promising targets for cancer therapy that drive tumor growth and progression." (PMID 37654845, 2022). "EGFR, a receptor PTK, is upregulated in most epithelial cancers, and EGFR signaling contributes to cancer cell proliferation and survival." (PMID 35356799, 2022). "The developed aptasensor has been used to directly determine an epidermal growth factor receptor (EGFR) protein, as well as living Michigan cancer foundation-7 (MCF-7) cells." (PMID 35808255, 2022). "The epidermal growth factor receptor (EGFR), which is a transmembrane receptor tyrosine kinase that is overexpressed in several human cancers, has become an important therapeutic target in mCRC." (PMID 35242708, 2022). "These are, to our knowledge, the first single-molecule observations of the effect of EGFR- and HER2-targeting anti-cancer drugs on living human cancer cells." (PMID 35612280, 2022). "Biopsy, the gold standard for EGFR mutation detection, may be limited by the lack of available tissue samples because biopsy and cytology specimens are first used for histological testing to confirm cancer type." (PMID 35422977, 2022). "Our study indicates that cholesterol/EGFR/Src/Erk/SP1 axis-induced ERRα re-expression promotes survival of gefitinib and osimertinib-resistant cancer cells." (PMID 35303882, 2022). "Epidermal growth factor receptor (EGFR) is a carcinogen and activates various carcinogenic signaling pathways in cancer cells." (PMID 36532716, 2022). "This is in keeping with an intricate network connecting TET1 to the hypomethylation and activation of cancer-specific oncogenic pathways, including PI3K, EGFR, and PDGF." (PMID 35755313, 2022). "Our results showed that UTX was a molecule of the downstream network of EGFR, and GSKJ4 showed anti-cancer effect." (PMID 34661759, 2022).
cancer (continued). "For instance, OSCC is one of the cancers typically treated with the anti-EGFR antibody cetuximab; however resistance to this drug has been observed, since OSCC release EVs containing EGFR in response to EGF or cetuximab." (PMID 35646668, 2022). "Of note, combination therapy to target both Src and EGFR in NSCLC has been implemented with the Src-EGFR crosstalk inhibitor AC-93253 iodide, which showed promising results by impeding cancer growth and cell motility." (PMID 36547158, 2022). "In the present study, it is interesting whether combining first-generation EGFR-TKI with Se/FO increases the in vivo anti-cancer efficacy over that of EGFR-TKI alone in NSCLC without the EGFR mutation, although the KRAS mutation inhibitor is currently available." (PMID 36547898, 2022). "Epidermal growth factor receptor (EGFR) and anaplastic lymphoma kinase (ALK) are two paradigms of cancer driven genes that provide highly efficient therapeutic targets." (PMID 35876652, 2022). "In order to target cisplatin delivery and reduce its systemic cytotoxicity, anti-epidermal growth factor receptor (EGFR) antibody, which is against EGFR overexpressed on the surface of some cancer cells, can be attached to CDDP liposomal nanoparticles." (PMID 36457031, 2022). "Since the EGFR/RAF/MEK/ERK pathway is essential for normal cellular processes, indiscriminately inhibiting this pathway would target both normal cells and cancer cells." (PMID 35668076, 2022). "In EGFR-targeted therapy for NSCLC, there is experimental evidence that HER3 plays a key role in cancer cell survival and drug resistance." (PMID 36313314, 2022). "CiRS-7/miR-7/EGFR, circ_0067934/PI3K/AKT, circ_0067934/miR-1301-3p/HMGB1, and circ_0062389/miR-1179/HMGB1 regulate the EMT process and thus cancer tissue invasion/metastasis." (PMID 36230649, 2022). "OGN can reverse EMT by suppressing the EGFR/AKT/Zeb-1 axis, which is an indicator of increased survival and decreased cancer recurrence in colorectal cancer." (PMID 36421687, 2022). "In other cancers, MET monotherapy has demonstrated limited effectiveness due to activation of bypass pathways such as EGFR and HER." (PMID 35325006, 2022). "In our study, this inhibitory activity on HepG2 cancer cells was supported by an inhibition in the expression MMP-9, VEGFR2 and EGFR." (PMID 36284117, 2022). "Taken together, EGFR, PI3K/Akt, and mTOR signal pathways can control SREBP-1 expression and activation to regulate its downstream pathways in cancers." (PMID 35912181, 2022). "Altogether, the protein expression analysis confirmed enrichment of FOXP3-positive cells in ALK-positive cancer and depletion of CD8-postive cells in EGFR-positive cancer." (PMID 34125345, 2022). "Utilizing the patient datasets from Pan-Cancer (c-Bioportal), we observed a significant positive correlation between DDR1 expression and expression of genes BCR, EGFR, and ERBB2." (PMID 35664781, 2022). "One prominent resistance mechanism to EGFR‐TKIs, KRAS, or MEK inhibitors is the reactivation of ERK1/2 signaling, which can drive cancer cell survival and proliferation." (PMID 35838331, 2022). "In the context of EGFR activation, the role of EREG was studied in many cancers and remains controversial, because either protective or pathogenic effects were demonstrated." (PMID 35159237, 2022). "The activation of the EGF/EGFR signalling pathways facilitates the EMT process and enrichment of ALDH+/CD44 high cancer stem cells (CSCs)-like cells with increased invasiveness/metastasis potentials both in vitro and in vivo." (PMID 35681586, 2022). "PRL3 promoted metastasis of cancer cells by regulating a diverse downstream prometastatic effector molecule, via NF-κB pathway, AKT, STAT3, EGFR, IL-8 and CCL26." (PMID 35246503, 2022). "The EGFR pathway in GBM is regulated by another miRNA, miR-7, which is a major regulator of cancer pathways, and its forced expression decreases viability and invasiveness in primary GBM cells." (PMID 36009578, 2022).
cancer (continued). "Multi-targeted inhibitory properties were observed against VEGFR-2 (vascular endothelial growth factor receptor-2) and EGFR (epidermal growth factor receptor) in both MCF7 (breast) and HCT116 (colon) cancer cells." (PMID 36349009, 2022). "EGFR, KIT, MET, PPARG, and STAT5A were enriched in the Pathways in cancer, CAV1, EGFR, and MET were enriched in the Proteoglycans in cancer, and MET and PPARG were enriched in the Transcriptional misregulation in cancer." (PMID 35063044, 2022). "The synthesized novel dual PROTACs can successfully and simultaneously degrade EGFR and poly(ADP-ribose) polymerase (PARP) in cancer cells." (PMID 35840984, 2022). "Human cancer tissues express high levels of growth factors and their receptors, such as EGF/EGFR, which exhibit autocrine or paracrine regulation of cancer growth." (PMID 35502895, 2022). "Hence, targeting EGFR may be an effective approach to treat cancer." (PMID 36440230, 2022). "EGFR is the first identified RTK functioning as an oncogene and found to regulate cancer development by triggering distinct pathways, including RAS/RAF/MEK/ERK, PI3K/AKT/mTOR, Src kinases, and STAT transcription factors." (PMID 35931120, 2022). "An in silico study on three main enzymes EGFR, CDK2 and CDK4 proved the effectiveness of trans-anethole in inhibiting these enzymes and so the consequences of cancer progression." (PMID 35850583, 2022). "A previous study suggested that combining anti-EGFR and anti-STAT3 agents would prove a practically effective mode of cancer suppression." (PMID 36145523, 2022). "Several MEK1 mutations have been detected not only in primary (pre-treatment) cancers but also in recurrent cancers in patients treated with ERK pathway-targeted drugs (e.g., EGFR, Raf, or MEK inhibitors)." (PMID 35831322, 2022). "The targets in the cancer pathways (SRC, EGFR, ESR1, PTGS2, and APP) were used for molecular docking analysis with all active compounds." (PMID 36561345, 2022). "The analysis suggested a few common cancer-related pathways like Wnt, angiogenesis, TGF-beta, p-53, PI3K, and p-38 MAPK, Notch, EGFR, and NF-κB pathways." (PMID 36276982, 2022). "In a similar way, MMP9 was shown to regulate the activity of nerve growth factor (NGF)-induced transmembrane receptor tyrosine kinase A (TrkA), EGFR/HER, and insulin receptor (IR) signaling in cancer cells." (PMID 35406619, 2022). "The anti-CD3 x anti-EGFR construct in the clinical setting is limited to EGFR expressing cancers, however, the majority of CRC tumors overexpress EGFR." (PMID 35177811, 2022). "Since both UTX and EGFR signaling pathways play important roles in cancer, we aimed to clarify the role of UTX in NSCLC and the regulation mechanism between UTX and EGFR signaling pathway." (PMID 34661759, 2022). "In this study, we have systemically identified master regulators driving prognosis in patients with LUAD, treated with surgical resection, EGFR-TKI, and ICB-based cancer immunotherapy." (PMID 36304306, 2022). "TSP-1 is known to bind integrins, Low Density Lipoprotein Receptor Related Protein-1 (LRP1), EGFR, TGF-beta, urokinase-type Plasminogen Activator (uPA), and VEGF-A, all of which are expressed on, or bind to, cancer cells (GEMICCL)." (PMID 36546919, 2022). "ITCs 451–455 and 457 were evaluated for their ability to inhibit the proliferation of the highly epidermal growth factor receptor (EGFR-TK) expressed in human epithelial cancer cells A431 and HaCaT cancer cells." (PMID 35268851, 2022). "Recent studies demonstrate that oncogenic signaling pathways such as PI3K/AKT/mTOR, the epidermal growth factor receptor (EGFR), Ras/MAPK, Notch, and Wnt/β-catenin, play a fundamental role in cancer therapy." (PMID 35745567, 2022). "TEAD1 is a key TF in various oncogenic signaling pathways, including the Hippo, Wnt, TGFβ, and EGFR pathways, and plays critical roles in EMT, metastasis, drug resistance, and cancer stem cells." (PMID 35999456, 2022).